FOLR1 (folate receptor alpha)
Diseases named in the same sentence as FOLR1 in open-access papers (continued):
Sharing a sentence is not in itself a finding about the gene and the disease.
cancer (continued). "Expression data in the Cancer Cell Line Encyclopedia (CCLE) database indicate high FOLR1 gene expression in the majority of cell lines of all lineages, including those of testicular origin." (PMID 39996761, 2025). "Pafolacianine targets is the folate receptor alpha (FRα), a cell surface glycoprotein that is overexpressed in many cancers including non-small cell lung cancer (NSCLC)." (PMID 41087662, 2025). "Cancer cells are highly dependent on FOLR1 internalization to initiate folate metabolism for DNA replication, methylation, and repair." (PMID 40029935, 2025). "FA, a high-affinity ligand for folate receptor alpha (FRα) frequently overexpressed on cancer cells, was next attempted for site-specific conjugation with CD9-CD38 exosomes." (PMID 41419470, 2025). "Amygdalin, a naturally occurring compound that is also known as vitamin B17, enhances the targeting efficiency of cancer treatment due to its preferential binding to folate receptor alpha, which is overexpressed on cancer cells." (PMID 40303301, 2025). "For engagement of the cancer cells, we exploit folate receptor alpha (FRα) that is over-expressed on ~40% of human cancers and induce cancer cell engagement with the CAR T cells by injection of a folate-fluorescein (folate-FL) bispecific adapter." (PMID 40034702, 2025). "Folate is an essential vitamin and a high-affinity ligand for the FOLR1, which is highly upregulated in ovarian, lung, breast, and other cancers." (PMID 38396800, 2024). "The success of these in vitro studies has prompted the investigation of the effectiveness of using anti-FOLR1 T cells to treat other cancer types." (PMID 38256120, 2024). "We first analyzed the gene (RNA-seq) and protein (reverse-phase protein array) expression data of FOLR1 in 363 cancer cell lines, including 17 ovarian cell lines, from the Cancer Cell Line Encyclopedia (CCLE), publicly hosted on the DepMap portal." (PMID 39596024, 2024). "OTL38 is a folate analog ligand conjugated to S0456, an indocyanine green-like dye which targets the folate receptor alpha (FOLR1) that is overexpressed in specific cancers." (PMID 38633313, 2024). "In these cells, nearly 80 glycans were identified at the N69 glycosite of folate receptor alpha (FOLR1), highlighting the intricate relationship between glycosylation processes and cancer progression." (PMID 39372389, 2024). "FA incorporation led to enhanced targeting of glioblastoma cancer cells due to the overexpression of folate receptor 1 (FOLR1), also evident in several other cancers." (PMID 39065565, 2024). "According to recent research, FOLR1 is involved in a high number of intracellular signaling networks, many of which impact cancer cells, namely JAK-STAT3, ERK1/2, and as a transcription factor signaling pathways." (PMID 38915965, 2024). "For these reasons, leucovorin has been used to treat epileptic patients having mutations in the folate receptor alpha gene, FOLR1101, as well as in the context of cancer chemotherapy to decrease the toxic effects of methotrexate, an inhibitor of the DHFR." (PMID 39537633, 2024). "For example, PCa lacks appreciable FOLR1 expression invalidating folate–miR-34a as a therapeutic in this cancer." (PMID 38396800, 2024). "Folate receptor alpha (FRα) was the most abundant and overexpressed isoform in cancer tissue compared to normal tissue." (PMID 38915965, 2024). "This meta-analysis highlighted the prognostic value of FOLR1 across various cancer types, a finding that has been corroborated by more recent studies, including one focusing on rectal cancer." (PMID 38256120, 2024). "FOLR1 mRNA expression was significantly correlated with protein expression in both cancer cell lines (r = 0.82, p = 5.7 × 10−76) and ovarian cell lines (r = 0.87, p = 1.03 × 10−5)." (PMID 39596024, 2024). "Folate receptor alpha (FRα), encoded by the FOLR1 gene, has attracted considerable interest due to its high expression in several cancer types including those of lung and breast." (PMID 37711615, 2023).
cancer (continued). "Folate receptor alpha (FRα) is a membrane-bound protein that is overexpressed in a number of cancers." (PMID 35053365, 2022). "Folate receptor alpha (FRα) is a cell surface protein involved in the biosynthesis of nucleotide bases, amino acids, and methylated compounds, playing an important role in cancer development." (PMID 35414783, 2022). "EC17 is a good choice because the folate receptor-alpha (FRα) is highly expressed in some epithelial carcinomas, including pulmonary adenocarcinomas." (PMID 35959120, 2022). "As a result of its strong safety profile in clinical trials and its specific ability to target FOLR1-positive tumors, farletuzumab is an attractive antibody for use in ADCs targeting FOLR1-positive cancer patients." (PMID 33535554, 2021). "Folate receptor alpha (FRα) is known as a biological marker for many cancers due to its overexpression in cancerous epithelial tissue." (PMID 33670773, 2021). "The unleashed eribulin eradicates the FOLR1-expressing cell and then penetrates surrounding tissues, killing other cancer cells in what is known as the bystander killing effect." (PMID 33535554, 2021). "Drug targeting is a progressive area of research with folate receptor alpha (FRα) receiving significant attention as a biological marker in cancer drug delivery." (PMID 34500740, 2021). "One study developed porphyrin-lipid NPs (porphysomes) targeted to FOLR1, another FR overexpressed in multiple forms of cancer." (PMID 33121022, 2020). "We evaluated by RT-qPCR the expression of FOLR1 transcripts in four cancer cell lines: MiaPaCa-2, Panc-1, Capan-1, and Capan-2." (PMID 31936786, 2020). "The folate receptor alpha (FRα) is an interesting target for imaging and therapy of different cancers." (PMID 32270313, 2020). "Target cell lysis correlated with T-cell activation and secretion of granzyme B induced by the crosslinking through FOLR1-positive cancer cells as it was recently shown for CEA TCB2." (PMID 32581215, 2020). "This distribution was due to the expression of Folr1 on cancer cells and the presence of FA on the nanoparticles since there was significantly less uptake in T-47D tumors when N2-APTMS were injected." (PMID 29566719, 2018). "A variety of FOLR1 targeting approaches, including folate-drug conjugates, monoclonal antibodies, and T cell therapies, have been developed for the treatment of cancer." (PMID 29874279, 2018). "To test the functionalization of the YPMS@PpIX@FA nanoparticles, we screened various mouse cancer cell lines to identify cells with high and low expression of Folr1 mRNA." (PMID 29482561, 2018). "Farletuzumab, a monoclonal antibody targeting FOLR1, induces the death of cancer cells expressing FOLR1 by antibody-dependent cellular cytotoxicity (ADCC), complement-dependent cytotoxicity (CDC), and inhibition of Lyn kinase substrate phosphorylation." (PMID 29874279, 2018). "One promising, emerging, druggable target for cancer therapy is folate receptor alpha (FRα), which is a high-affinity receptor for folate (vitamin B9)." (PMID 30651934, 2018). "It has been reported that, in patients, cancer cells often express a high level of folate receptor (FOLR1) due to their metabolic needs and FA is a validated mean to target nanoparticles to cancer cells." (PMID 29482561, 2018). "To reproduce this in vitro, we sought to identify a cell line with a high expression of folate receptor (Folr1hi), and we determined the level of expression of folate receptor Folr1 in different human cancer cell lines using RT-qPCR." (PMID 29566719, 2018). "Folate receptor alpha (FR) is highly expressed in some forms of cancers such as ovarian cancer and in up to 80% of breast cancer tumors." (PMID 29566719, 2018). "Glycophosphatidyl inositol (GPI)-anchored folate receptor alpha (FRalpha) is up-regulated in many types of cancer cells." (PMID 28978186, 2017).
cancer (continued). "We noticed that FOLR1 mRNA expression is significantly stronger in both the tubal healthy epithelium and the type II cancers than in normal ovarian epithelium together with borderline tumours and type I cancers." (PMID 27485273, 2016). "One-year survival analysis showed in type I cancers an independent better outcome for strong expression of FOLR1 in FIGO stage III and IV." (PMID 27485273, 2016). "Type I cancers are known for their poor constitutive responsiveness to chemotherapy including platinum agents and, as already mentioned, FOLR1 expression has been found to be significantly weaker in type I and type II cancers." (PMID 27485273, 2016). "The odds ratio to predict platinum refractority/resistance in case of high FOLR1 expression cancers, in the whole cohort, was 2.013 (1.086-3.731) p = 0.018." (PMID 27485273, 2016). "In type I cancers, however, strong FOLR1 expression has been found to be a reliable indicator of improved platinum responsiveness reflecting a transient better one-year follow up outcome in highly FOLR1 expressing type I cancers." (PMID 27485273, 2016). "The folate receptor alpha (FR-α) has already been identified as a suitable target for cancer therapy and imaging." (PMID 26248049, 2015). "A biomarker of recent interest in the cancer field is folate receptor alpha (FOLR1), a membrane-bound protein with high affinity for binding and transporting folate into cells." (PMID 25816016, 2015). "Over-expression of folate receptor alpha on cancer cells has been frequently exploited for delivery of folate-targeted imaging and therapeutic agents to tumors." (PMID 25909292, 2015). "Taken together, our data suggest that patients with triple negative cancers expressing high FOLR1 expression represent an important population of patients to consider for clinical trials evaluating targeted anti-FOLR1 therapy." (PMID 25816016, 2015). "Sera of cancer-free men and women (N = 60) enrolled in a population-based cohort study in Alberta, Canada were analyzed for FOLR1 protein using an electrochemical luminescence immunoassay." (PMID 24810481, 2014). "Studies in several cancers have found that cell surface proteins such as the folate receptor alpha (FOLR1), a highly expressed protein on ovarian and other epithelial derived cancers can be exploited in a theranostic context." (PMID 24982846, 2014). "Therefore, FOLR1-targeting has long been used as an effective strategy for cancer imaging and selective targeting of tumors, and several FOLR1-targeting drugs are in phase II/III clinical trials." (PMID 41012497, 2025). "Folate receptor alpha (FORα) has been used to detect and treat cancer for years." (PMID 40830177, 2025). "We evaluated FOLR1 mRNA expression in 1832 cancer ovarian samples and 30 normal ovarian samples." (PMID 39596024, 2024). "The concentration of FOLR1 depends on the clinical stage of the cancer and its histology, grade, and size; therefore, FOLR1 serum levels are much higher in the case of aggressive and advanced tumors of the HGSOC type while being lower in mucinous and early-stage tumors." (PMID 38275400, 2024). "This may be indicative of a higher sensitivity of CAR candidate 12 towards cancer cells with low FOLR1 expression." (PMID 39594628, 2024). "However, further research is needed to explore the molecular mechanism of the effect of FOLR1 on cancer cell behaviour." (PMID 38057830, 2023). "OTL38 targets the folate receptor alpha (FRα) overexpressed in several cancers." (PMID 37195806, 2023). "Exploiting the overexpression of folate receptor α (FOLR1) in many cancer types, folate-caged degraders have been designed, envisioned to be transported preferentially into cancer cells, where intracellular hydrolase catalysis activates the degrader by release of the folate caging group." (PMID 35983982, 2022).
cancer (continued). "Since folate receptor α (FOLR1) is low in normal tissues but is highly expressed in many human cancers, including multiple myelom (MM), lymphoma, and non-small cell lung cancer (NSCLC), folate-conjugating strategy is one of the commonly used drug delivery methods." (PMID 35680848, 2022). "Moreover, mature FOLR1 is an N-glycosylated protein that is predominantly expressed on epithelial cells and is dramatically upregulated on many carcinomas." (PMID 35938042, 2022). "Therefore, after selectively binding to FOLR1 and being transported into cancer cells through receptor-mediated endocytosis, the linker unleashes its cytotoxic payload, eribulin, as a result of lysosomal protease cleavage." (PMID 33535554, 2021). "FOLR1 transcripts is expressed in the four different cancer cell lines." (PMID 31936786, 2020). "Cytometry analysis confirmed the protein expression of FOLR1 by the four cancer cell lines." (PMID 31936786, 2020). "MAX (a MYC interacting partner), miR-150, miR-133a, FOLR1, E2F NCAM1, GAS2L3 and ATF5 are the most significantly associated upstream regulators, while cancer, neurogenesis, metastasis and cellular development are the most important biological functions affected in this subgroup." (PMID 32591022, 2020). "Several studies have shown that FOLR1 is a good target for various cancers." (PMID 29874279, 2018). "These properties show that FOLR1 is an attractive candidate as a target for cancer therapy." (PMID 29874279, 2018). "Therefore, FOLR1 is an attractive candidate for the targeted treatment of cancer and the FOLR1 targeting strategies can increase treatment success rates." (PMID 29874279, 2018). "Mirvetuximab soravtansine (IMGN853) is an antibody-drug immunoconjugate that consists of a humanized monoclonal antibody (M9346A) targeting folate receptor alpha (FRα)-positive cancer cells attached to a highly potent cytotoxic maytansinoid, DM4." (PMID 30155674, 2018). "Folate receptor α (FOLR1) is often overexpressed in cancer cells of patients and folic acid (FA) has been used to increase the affinity of a variety of anti-cancer agents for cancer cells." (PMID 29482561, 2018). "Because the Folr1 targeted chemotherapeutic drug delivery can reduce the dosage of agents and side effects, increase the efficacy and specificity, as well as bypass the drug resistance, Folr1-Ara-C has shown promising application in a wide variety of cancers." (PMID 28416738, 2017). "In addition, FA as the legend for Folr1 shows a high-affinity of binding after derivatization and has been defined as the most widely investigated delivery for cancer therapy." (PMID 28416738, 2017). "PPF-curcumin is internalized into the cancer cells via FOLR1-mediated endocytosis." (PMID 29296172, 2017). "We have also observed that PPF-curcumin exhibits enhanced therapeutic efficacy in vitro, compared to either PLGA-curcumin or free curcumin, probably due to uptake of the cucrumin via folate receptors (FOLR1) reported to be over-expressed in almost all cancer types." (PMID 29296172, 2017). "Intraoperative fluorescence imaging of the folate-receptor alpha (FRα) could support completeness of resection in cancer surgery." (PMID 27014973, 2016). "Two orders of magnitude can be distinguished regarding FOLR1 expression: one is the clustering of type I cancers together with borderline tumours and healthy ovarian epithelium and the second is the merging of type II cancers with healthy fallopian epithelium." (PMID 27485273, 2016). "Since folate receptor alpha is expressed exclusively by the epithelial cells themselves in these tumors, we can now link the expression of these 2 isoforms of folate receptor to the pathogenesis of cancer." (PMID 25971554, 2015).
cancer (continued). "Before serum FOLR1 protein can be considered for investigation as a marker for early cancer detection, it is important to investigate if it is associated with the same factors reported for total serum folate binding capacity in healthy individuals and to clarify the range of normal serum values." (PMID 24810481, 2014). "Furthermore, the upregulation of FOLR1 was correlated with the drug resistance of cancer cells." (PMID 38057830, 2023). "The positive association between serum FOLR1 concentration and female gender independent of an age effect suggests caution against statements to exploit serum FOLR1 for early cancer detection without further understanding the biological underpinnings of these observations." (PMID 24810481, 2014). "The labeled antibody showed strong binding to the folate receptor alpha on IGROV1 and SW620 cancer cells." (PMID 41283276, 2025). "Both FOLR1-CAR KHYG-1, a natural killer cell line and FOLR1-CAR T cells has been demonstrated to recognized FOLR1-expressing GC cells in a MHC-independent manner: this fact promotes the release of several cytokines and induce cancer cell apoptosis." (PMID 32751137, 2020). "The genes selected using this method included NCOA3, HOXA1, FOLR1, SOCS1, and PIK4CA, which showed similar expression patterns related to survival in patients with cancer." (PMID 29854877, 2018). "In FIGO stage III and IV type I cancers showed independent better PFS and OS for high levels of FOLR1 mRNA expression." (PMID 27485273, 2016). "In univariate survival analysis, when the cohort of cancers was dichotomized along the median value in high and low FOLR1 expression cancers, we revealed significantly reduced PFS (p = 0.022) and OS (p = 0.029) in cancers with strong FOLR1 mRNA expression." (PMID 27485273, 2016). "Folate receptor alpha (FOLR1) has been identified as a potential prognostic and therapeutic target in a number of cancers." (PMID 25816016, 2015). "FR/FRα/FOLR1 is highly over-expressed (40–90%) on primary and metastatic human cancers of the ovary, lung, breast, colon, endometrium, kidney, and brain, but has only limited distribution in healthy tissues." (PMID 23658721, 2013). "Treatment with HGF or TGF-β1 can increase the expression of the glycosyltransferase FUT8 and up-regulate the core fucosylation of N-glycans on FR FOLR1, thus enhancing folate uptake, and eventually promoting epithelial–mesenchymal transition (EMT), which is the key process of cancer metastasis." (PMID 38931227, 2024). "Folate-ARV-771 demonstrated efficient BRD2/3/4 protein degradations in cancer cells through a mechanism that is dependent on folate receptor alpha (FOLR1), but not in normal non-cancerous ones." (PMID 38389844, 2024). "Folate receptor (FR) alpha (FOLR1) and beta (FOLR2) are membrane-anchored folate transporters that are expressed at low levels in normal tissues, while their expression is strongly increased in several cancers." (PMID 38212621, 2024). "An alternative approach for controllable action of PROTACs in cancer cells could be taking advantage of cancer-specific receptors or transporters, such as HER2 and FOLR1 for the guided delivery of PROTACs into cancer, but not normal cells." (PMID 34350175, 2021). "This design along with the removal of the N-glycosylation site in the Fc module, which is required for Fcγ receptor binding, eludes the systemic activation of CD3+ T cells in the absence of FOLR1+ cancer cells." (PMID 31497024, 2019). "Noteworthy is the significant higher levels of FOLR1 mRNA expression in high grade cancers, advanced stage, non-optimally debulked tumors and in platinum sensitive cancers." (PMID 27485273, 2016). "Accordingly, univariate survival analyses for the entire cohort of patients revealed poor clinical outcome in terms of PFS and OS when FOLR1 mRNA expression was up-regulated, but this was not verified when type I and type II cancers were assessed separately." (PMID 27485273, 2016).